FGF21 (fibroblast growth factor 21)
Diseases named in the same sentence as FGF21 in open-access papers (continued):
Sharing a sentence is not in itself a finding about the gene and the disease.
diabetes (continued). "In addition, FGF21-KO mice were more sensitive to diabetes-induced renal injury, which was remarkably prevented by FGF21 treatment through the mechanism of lowering lipid accumulation, and by anti-inflammation, anti-oxidation, and anti-fibrosis effects." (PMID 24349242, 2013). "Furthermore, systolic pressure, adiponectin, proteinuria, β2 microglobulin, phosphate, albumin and LVH were significantly correlated with circulating FGF21 levels after adjustment for BMI, gender age and diabetes mellitus in all CKD subjects." (PMID 21525989, 2011). "We have also showed that diabetes and hypertension have additional effects on FGF-21 levels in CHD patients, which is supported by the fact that serum FGF-21 levels in CHD individuals with diabetes, hypertension, or both were higher than in the CHD individuals without these complications." (PMID 21206918, 2010). "While there is ongoing debate about whether FGF21 negatively affects bone mineral density, the effects of these myokine-based gene therapies on bone health, particularly in the context of osteoporosis and diabetes, have yet to be fully studied." (PMID 40568561, 2025). "FGF21 was found to be predominantly expressed in the liver, and its functions were completely unknown until 2005 when it was presented as a novel metabolic regulator with potential for diabetes therapy." (PMID 38379823, 2024). "Thus, FGF21 can be used as a predictive marker for type 2 diabetes mellitus." (PMID 39341924, 2024). "However, the relationship between FGF21, body shape, and blood pressure in patients with diabetes remains unknown." (PMID 37424900, 2023). "Furthermore, the cardioprotective effect of FF in type 1 diabetes mellitus is dependent on FGF21." (PMID 36843938, 2023). "These evidence to show FGF21 may be used as a biomarker in the diagnosis of diabetes." (PMID 37576954, 2023). "In addition, a number of studies have reported that FGF-21 could be an independent predictor of fatty liver, chronic liver failure, coronary heart disease, and prognosis in patients with diabetes." (PMID 37658393, 2023). "This may be related to the resistance of FGF21 in the long-term course of diabetes." (PMID 37576954, 2023). "Although the decrease in serum insulin to the levels near normal values might be one of the factors to compensate deleterious effects of diabetes, however, the reason for high levels of FGF21 relation to phenolics and flavonoids as well as glibenclamide needs furder examination." (PMID 34233693, 2021). "However, whether the knockout of miR-21 mediated activation of EAT browning could promote FGF21 secretion and whether EAT browning-derived FGF21 plays an endocrine role on atrial fibroblasts in diabetes need to be further explored." (PMID 34484568, 2021). "Although restoration of serum insulin to the levels near normal values might be one of factors to compensate deleterious effects of diabetes, however the resone for high levels of FGF21 relation to phenolics and flavonoids as well as glibenclamid needs furder examination." (PMID 34233693, 2021). "In this study, we provide the first observation that baseline FGF21/adiponectin ratio levels are increased in diabetes and could be a strong predictor of deterioration in glycemia over a median follow-up of 4.6 years, independent of the classical risk factors including FPG, 2hPG, and HbA1c." (PMID 34321008, 2021). "FGF21 level in patients with type 1 diabetes is lower than that in healthy subjects, implying that it may be important to maintain FGF21 level for treatment of diabetes." (PMID 32872333, 2020). "FGF21 may be able to improve metabolic homeostasis in diabetes." (PMID 32872333, 2020). "Giving that engineered FGF21 analog has been successfully applied for diabetes treatment in clinical, our results may extend the indication of the engineered FGF21 analog from metabolic disorders to hypoxia-related brain diseases such as brain ischemia and acute mountain sickness." (PMID 30842736, 2019).
diabetes (continued). "However, it remains unknown whether FGF21 is involved in insulin expression and secretion that are dysregulated in type 2 diabetes mellitus (T2DM)." (PMID 30461198, 2019). "However, it is largely unknown whether nonalcoholic fatty liver disease (NAFLD), a condition associated with both diabetes and FGF-21 levels, may explain or modify the association between FGF-21 and diabetes risk." (PMID 29021814, 2017). "However, the current analysis along with prior studies have shown that the association between FGF-21 and diabetes was independent of lipids (TG, HDL-C), inflammatory marker (hs-CRP) and liver enzymes (GGT, ALT)." (PMID 29021814, 2017). "In this Chinese population in Singapore, we found a strong dose-dependent association between higher serum FGF-21 levels and increased risk of incident type 2 diabetes in women but not in men, and the association was independent of liver enzymes and other diabetes risk factors." (PMID 29021814, 2017). "Therefore, FAP inhibitors could prove even more useful in treating diabetes and metabolic disorders than may be expected from extending the lifetime of FGF-21 alone." (PMID 26962859, 2016). "Besides those insulin-mimetic properties, FGF21 does not induce mitogenicity, hypoglycaemia or weight gain at any dose tested in diabetic or healthy animals or when overexpressed in transgenic mice 13; therefore, FGF21 shows a promise as an effective treatment of diabetes." (PMID 25823710, 2015). "Independent variables were set as metabolic risk factors (including age, diabetes duration, smoking status, presence of hypertension,ALT, GFR, HbA1c, waist circumference, dyslipidemia, anti-diabetic therapy, anti-hypertensives, lipid-lowering therapy and serum FGF21 levels)." (PMID 25850006, 2015). "In the present study, we tested the hypothesis that circulating levels of FGF19 and FGF21 correlate with each other, and that along with genes regulating hepatic pathways of bile acid synthesis are dysregulated in diabetes and in particular in patients that fail to remit diabetes after RYGB surgery." (PMID 25664662, 2015). "Despite the multiple salutatory effects of FGF21 on glucose and lipid metabolism in animals, circulating FGF21 levels are elevated in obese subjects and patients with impaired glucose tolerance, type 2 diabetes mellitus, dyslipidemia, and nonalcoholic fatty liver disease (NAFLD)." (PMID 26047614, 2015). "Thus, we next determined whether FGF21 had protective effect against diabetes-induced renal pathological changes, and if so, whether the possible protective mechanism was attributable to an anti-lipotoxic role." (PMID 24349242, 2013). "W-Y Cao and his coworkers engineered L. lactis to overexpress bioactive human fibroblast growth factor 21 (FGF21) (a metabolism regulator), and found it reduced body weight of diabetes (Db/Db) mice through the activity of brown adipose tissue." (PMID 41415685, 2025). "Fibroblast growth factor 21 (FGF21), a regulator of lipid and glucose metabolism, protects against diabetes-induced cardiovascular injuries but is inhibited by HDAC3." (PMID 40660005, 2025). "AP026, a FGF21 (fibroblast growth factor 21)/ GLP-1 (glucagon-like peptide-1) bifunctional protein, is currently undergoing phase 1 clinical development for the treatment of NASH and type 2 diabetes mellitus (T2DM)." (PMID 40636296, 2025). "One such biomarker, FGF-21, shows promising potential in predicting NAFLD in individuals with Type 2 Diabetes Mellitus (T2DM) due to its high sensitivity and specificity compared to other markers." (PMID 39617908, 2024). "Induction of diabetes increased VEGF, FGF21, and TGF-β serum levels and decreased circulating FLK-1 and sFLT-1 factors." (PMID 38584657, 2024). "Our previous studies showed that FGF21 downregulates NLRP3 inflammasome activity, inhibits VSMC proliferation and migration, and alleviates diabetes-aggravated neointimal hyperplasia." (PMID 38733164, 2024).
diabetes (continued). "FGF21 is also related to the transition from prediabetes to DM." (PMID 36594101, 2023). "However, drug therapy and disease course may be confounding factors in diabetes patients enrolled in previous studies, and the association between FGF-21 and newly diagnosed T2DM is still lacking in southern China." (PMID 37658393, 2023). "In addition, FGF21 may also be used as a biomarker in the diagnosis of diabetes in the future." (PMID 37576954, 2023). "Serum level of FGF21 was increased, following a diagnosis of VDs including CAS and HP during diabetes, which is possibly a response to accelerated metabolic demands." (PMID 38057786, 2023). "FGF21 has emerged as the preferred therapeutic target FGF for metabolic diseases such as non-alcoholic steatohepatitis (NASH), metabolic syndrome, and diabetes mellitus (DM)." (PMID 36699319, 2022). "FGF21 mediated FGFR1 activation enhanced ERK1/2 phosphorylation, p38 MAPK activity, and AMPK activation, thereby impeding diabetes-induced apoptosis." (PMID 35983184, 2022). "Diabetes also induced oxidative stress in the EPCs,17 and the DHE staining results showed that HG significantly increased superoxide levels in EPCs, whereas FGF21 treatment decreased superoxide levels." (PMID 33599110, 2021). "We also found that diabetes was related to increased expression of nine proteins, IL-18R1, CCL11, CDCP1, OPG, HGF, TGF-α, CCL20, IL-6 and FGF-21." (PMID 34385358, 2021). "Serum FGF21 levels and FGF21/adiponectin ratio increased gradually with the deterioration in glycemic control from NGT to prediabetes and diabetes, while serum adiponectin concentrations progressively decreased (all p for trend < 0.001)." (PMID 34321008, 2021). "To improve this condition, we designed double gene-modified MSCs (FGF21 and GLP1) to achieve multiple repair effects in the treatment of diabetes." (PMID 33588950, 2021). "Human clinical trials have demonstrated the efficacy of some FGF21-based analogs in the reduction of body weight and treatment of dyslipidemia, NAFLD, and type 2 diabetes mellitus." (PMID 34943946, 2021). "In our study, baseline FGF21/adiponectin ratio increased progressively with the degree of dysglycemia from NGT to prediabetes and diabetes, and it was positively correlated with FINS and HOMA-IR." (PMID 34321008, 2021). "The aim of this study was to evaluate whether FGF21, galectin-3 and copeptin can be used as biomarkers to identify HFpEF in patients with confirmed type 2 diabetes mellitus (DM)." (PMID 34573919, 2021). "Last, the crosstalk between myokines (e.g., interleukin-6, irisin, and fibroblast growth factor 21) and adipokines (e.g., adiponectin, adipocyte fatty acid-binding protein) is thought to contribute to SMFD in diabetes." (PMID 32630360, 2020). "Moreover, recent studies have reported an interaction between FGF-21 and sex in its association with atherosclerosis and bone mineral density, with an association observed in women but not in men, but this has not been studied in the context of diabetes." (PMID 29021814, 2017). "The deletion of FGF21 was accompanied by a slight compensative up-regulation of cardiac FGFR1 mRNA under basal conditions, which was significantly amplified by diabetes in FGF21KO mice." (PMID 25823710, 2015). "Serum FGF21 levels were significantly higher in CHD patients, and were even higher in CHD patients with diabetes, and hypertension." (PMID 25071723, 2014). "Administration of FGF21 significantly prevented both FFA- and diabetes-induced renal damage partially by decreasing renal lipid accumulation and suppressing inflammation, oxidative stress, and fibrosis." (PMID 24349242, 2013). "Thus, we next determined whether FGF21 can protect renal cells from apoptosis induced by diabetes." (PMID 24349242, 2013).
diabetes (continued). "Circulating levels of FGF21 were found to strongly correlate with serum phosphate, creatine and CRP levels in CKD subjects after adjustment for BMI, gender, age and diabetes mellitus." (PMID 21525989, 2011). "The therapeutic potential of FGF1 in diabetes treatment also provides valuable insights for its potential clinical application in MASLD, especially given the significant progress made with FGF21—another member of the FGF1 family—in MASLD therapy and drug development." (PMID 41513602, 2026). "Parameters such as bone mineral density (BMD), trabecular thickness, and bone volume fraction (BV/TV) remained unchanged, suggesting that FGF21’s metabolic benefits do not necessarily compromise skeletal integrity in diabetes." (PMID 40568561, 2025). "While clinical development has focused on metabolic diseases such as diabetes and NAFLD, emerging evidence indicates that FGF21 also exerts antitumor effects in cancers including hepatocellular and prostate carcinoma, potentially through modulating autophagy, glycolysis, and ferroptosis." (PMID 41426308, 2025). "This study demonstrates positive associations of CDCP-1, FGF-21, IL-8, IL-18, eotaxin/CCL11, MMP-10, TNFRSF9, CCL25 and IL-10RB with depressive symptoms in people with diabetes without interaction with diabetes type." (PMID 39799156, 2025). "Other molecules which may play a role in the pathogenesis of CKD in MASLD are the hepatokines, in particular fibroblast growth factor-21 (FGF-21), whose levels increase in patients with type 2 diabetes mellitus, CKD and NAFLD/MASLD." (PMID 40722691, 2025). "Molecular insights implicated that the exercise response factor, fibroblast growth factor 21 (FGF21), maintained normal mitochondrial function by inducing the AMPK/FoxO3/SIRT3 signalling axis, thereby reversing diabetes‐induced hyperacetylation and dysfunction of the mitochondrial enzyme cluster." (PMID 38494853, 2024). "FGF21 levels in patients with DR were significantly higher than in non-DR patients with diabetes (SMD: 2.12, 95% CI [1.40, 2.84])." (PMID 39257905, 2024). "Understanding the complex relationship between FGF21 and diabetes and its complications has paved the way for novel pharmaceutical strategies to overcome T2DM." (PMID 39687000, 2024). "FGF21 levels were significantly higher in patients with DR than in non-DR patients with diabetes (SMD:2.12, 95% CI [1.40, 2.84]; I2 = 97%)." (PMID 39257905, 2024). "It has been shown that patients with diabetes were characterized by a higher FGF21 plasma concentration compared to patients without diabetes." (PMID 39064306, 2024). "We conclude that FGF21 levels were significantly higher in patients with DR than non-DR patients with diabetes, and that Klotho levels were significantly lower in patients with DR than non-DR patients with diabetes." (PMID 39257905, 2024). "There was a negative correlation between ln-transformed FGF21 levels and VA improvement (OR [95% CI] = 0.466[0.235,0.925], P = 0.029) after adjusted for age, gender, hypertension, diabetes, treatment and initial VA." (PMID 38789571, 2024). "Serving as a nexus between energy metabolism and innate immunity, FGF21 has evolved into a therapeutic target for diabetes, nonalcoholic steatohepatitis, and cardiovascular diseases." (PMID 38312833, 2024). "It must be noted that other antidiabetic, lipid-lowering, and blood-pressure-lowering agents did not affect the serum FGF21 levels in diabetes mellitus." (PMID 39452947, 2024). "Herein, FGF-21 analogs (NA-FGF) that were bio-fermented and purified from strain DNZY1 with longer-lasting hypoglycemic effects were used as the diabetes treatment drug, and N-2-HACC/CMCS MPs were employed as the carrier to construct the NA-FGF-N-2-HACC/CMCS MPs." (PMID 37514488, 2023). "In addition, a prospective study conducted in China over 5.4 years revealed significant changes in plasma FGF-21 levels in subjects with prediabetes (pre-DM) and T2DM as well as predicting the onset of diabetes." (PMID 37658393, 2023).
diabetes (continued). "The upregulation of cardiac FGF21 expression may increase SIRT1-mediated autophagy, which plays a key role in preventing diabetes-induced cardiac inflammation, oxidative stress, fibrosis, and dysfunction." (PMID 36843938, 2023). "Since the associations between HbA1c, FGF21, and IDOL were similar in subjects with and without diabetes, the two groups were combined in subsequent analysis." (PMID 37094639, 2023). "It was also demonstrated that FGF-21 provided additional value in the construction of the diabetes assessment model when combined with conventional noninvasive factors." (PMID 37658393, 2023). "Despite all this, the levels of FGF-21 and GDF-15 are likely influenced by age, body max index (BMI) and some certain diseases (e.g. heart failure, myocardial infarction, pulmonary hypertension, diabetes, metabolic syndrome, autoimmune diseases, and cancer)." (PMID 36935492, 2023). "FGF-21 is a therapeutic option for chronic metabolic diseases such as NASH and diabetes." (PMID 37288111, 2023). "It is generally thought that FGF21 could be a potential therapeutic agent for metabolic diseases, such as diabetes (including NASH), and synthetic recombinant human FGF21 (rhFGF21) has now entered clinical trials." (PMID 36967758, 2023). "Subsequently, restricted cubic splines were used to show the possibility of nonlinear relationships between FGF-21 and diabetes." (PMID 37658393, 2023). "Serum FGF21 level was significantly elevated in subjects with diabetes but was no longer significant after adjusting for age, sex, and BMI." (PMID 37094639, 2023). "Indeed, long-term administration of two other FGF-21-based bioengineered drugs, BMS-986036 and AKR-001, significantly reduced blood glucose levels in patients with diabetes." (PMID 36238554, 2022). "In addition, treatment with low-dose radiation (LDR) in combination with FGF21 significantly reduced diabetes-induced renal fibrosis, inflammation, and oxidative damage in mice with STZ-induced DN compared with LDR and/or FGF21 alone." (PMID 36387916, 2022). "Moreover, the long-acting FGF21 analogue PF-05231023 caused a marked reduction in serum triglycerides but not in body weight when intravenously administered to hypertriglyceridemic obese people, with or without diabetes, who were already treated with atorvastatin." (PMID 36362103, 2022). "In addition to metabolic function, FGF21 can penetrate the BBB, and has been reported to improve cognitive performance in diabetes and trauma models." (PMID 34071457, 2021). "Patients with diabetes had a more pronounced decrease in FGF21 levels after dexamethasone, as compared to patients without diabetes (− 233 pg/mL [95%CI − 322 to − 144 pg/mL] vs. − 80 pg/mL [95%CI − 143 to − 18 pg/mL]; p < 0.001)." (PMID 33846498, 2021). "Independent predictors of new-onset diabetes were identified using multiple logistic regression analysis, adjusted for age, BMI, waist circumference, SBP, triglyceride, HDL-C, LDL-C, hsCRP, sex, HOMA-IR, FPG, and FGF21/adiponectin ratio." (PMID 34321008, 2021). "This was because it has been shown that the serum FGF21 level has a positive and negative correlation with type 2 and type 1 diabetes mellitus, respectively." (PMID 32095207, 2020). "We measured levels of circulating FGF-21 in 207 overweight and obese Tanzanian males with or without type 2 diabetes mellitus (T2DM), and using statistical approaches, we explored their relationship with anthropometric and biochemical parameters." (PMID 30298107, 2018). "Our study demonstrated that the circulating FGF21 level was associated with the occurrence of CIN and subsequent renal function decline, regardless of the presence of diabetes." (PMID 30127382, 2018). "After adjusting for diabetes and LDL-c, the association between FGF21 levels and the risks of angina pectoris and UAP was not changed." (PMID 30185439, 2018).